IL18 (interleukin 18)
Diseases named in the same sentence as IL18 in open-access papers (continued):
Sharing a sentence is not in itself a finding about the gene and the disease.
Candida infection (5 papers, 2011 to 2021). "In agreement, administration of anti-IL-18 antibodies prior to systemic Candida infection depleted IFN-γ responses and enhanced fungal disease, whereas increasing IL-18 enhanced IFN-γ and Th1 responses which ultimately promoted protection." (PMID 33643264, 2021). "IL-18 appears to be broadly protective during Candida infection, although, as was found with Aspergillus, IL-18 acts through many distinct mechanisms to promote immunity." (PMID 33643264, 2021). "Administration of the microbial metabolite indole-3-aldehyde, known to stimulate the production of IL-22 via the aryl hydrocarbon receptor (AhR), promoted IL-18 expression and protection against Candida infection." (PMID 31681274, 2019). "The components of the NLRP3 inflammasome as well as IL-1β, IL-18, and the IL-1α/IL-1β receptor IL-1RI, are important for host survival from systemic candidiasis and prevention of dissemination of oropharyngeal candidiasis." (PMID 24967821, 2014). "We show that inflammasome driven IL-1β responses via both the NLRC4 and NLRP3 inflammasome are essential for epithelial antimicrobial peptide production, and other inflammatory responses including IL-18 and IL-17 in response to Candida infection." (PMID 22174673, 2011). "In our studies, in vivo IL-18 induction by Candida infection showed a similar pattern in mucosal tissues as IL-1β." (PMID 22174673, 2011). "Icld could promote the production of IL-22 via interaction with AHR, inducing the expression of IL-18 to inhibit Candida infection." (PMID 34361945, 2021). "Interleukin-18 is also vital for protection during Candida infection." (PMID 33643264, 2021).
cardiac arrhythmia (5 papers, 2019 to 2024). Any disturbances of the normal rhythmic beating of the heart or MYOCARDIAL CONTRACTION. "We hypothesized that IL-18 may heighten IL-6 effects on ventricular electrophysiology and arrhythmia risks." (PMID 39063055, 2024). "In our study, we found that the "inflammatory cytokines milieu" (in our study defined as elevated IL-18, sIL-2Rα and TNF-α) of permanent AF subjects is significantly associated with arrhythmia but not with an underlying cardiovascular disease." (PMID 32364529, 2020).
Chagas disease (5 papers, 2016 to 2024). A parasitic infection caused by Trypanosoma cruzi. "In the present study, three IL18 genetic variants were analyzed in four Latin American populations, being the largest genetic study conducted to date in Chagas disease." (PMID 31751351, 2019). "Analysis of larger cohorts would be required to definitively discard these IL18 variants as susceptibility markers for Chagas disease." (PMID 27027876, 2016). "Given the important role played by IL-18 in Chagas disease, in the present study we analyzed the association of three IL18 genetic variants with the predisposition to T. cruzi infection and the development of Chagas cardiomyopathy in different Latin America populations." (PMID 31751351, 2019). "This is consistent with the protective role that we observed for this allele in Chagas disease development, and support the hypothesis that major IL-18 levels could increase parasite clearance in early stages of infection." (PMID 27027876, 2016). "Several studies have highlighted the implication of IL-18 in the acute and chronic phase of Chagas disease." (PMID 31751351, 2019). "Interleukin-18 (IL-18), a pro-inflammatory cytokine produced mainly by macrophages, has been proposed to influence the development of Chagas disease." (PMID 31751351, 2019). "Interleukin 18 (IL18) is one of the genes that have been proposed to influence the development of Chagas disease." (PMID 27027876, 2016). "Our results suggest that IL18 is a relevant gene in Chagas disease, and could represent a valuable insight that may help to better understand the disease pathogenesis and the development of more efficient therapeutic strategies." (PMID 27027876, 2016). "IL-18 was shown to play an important role in early immunity to Chagas disease." (PMID 27027876, 2016). "On the other hand, a previous study showed that IL18 rs2043055 may modulate Chagas disease severity in a Brazilian population." (PMID 27027876, 2016). "In our study we were not able to find an association of any of the analyzed IL18 SNPs (including this one) with the severity of Chagas disease." (PMID 27027876, 2016). "While our data suggest that IL18 serum levels may not correlate with IL18 levels in cardiac tissue in Chagas disease, a larger future study should address a still possible IL18-reducing effect of HAART on Chagas cardiomyopathy." (PMID 33193300, 2020).
chronic hepatitis (5 papers, 2008 to 2023). An active inflammatory process affecting the liver for more than six months. "To identify the role of IL-12, IL-18, IL-21, and AchE in chronic hepatitis HBV patients, we compared the levels in different serum ALT groups." (PMID 36383803, 2022).
cutaneous melanoma (5 papers, 2010 to 2026). A primary melanoma arising from atypical melanocytes in the skin. "Current available data suggest that TNF-α and interleukins IL1B, IL-6, IL-8 and IL-18 can modulate the proliferation, survival and migration of cutaneous melanoma cells." (PMID 37047539, 2023). "IL-18 expression has been reported in some cutaneous melanomas." (PMID 24281094, 2010).
diabetic cardiomyopathy (5 papers, 2017 to 2024). Diabetic cardiomyopathy is a disorder of the heart muscle in people with diabetes. "Recent research found that increased IL-18 was involved in the pathogenesis of diabetic cardiomyopathy and expressed in the renal and retinas of the STZ-induced diabetic rats." (PMID 38529047, 2024). "BMP-7 treatment showed a significant reduction (p < 0.001) in the expression of IL-1β, and IL-18 compared to the diabetic cardiomyopathy." (PMID 34685620, 2021). "Furthermore, Sun and Ding70 proposed that diabetic cardiomyopathy is an inflammatory disease exacerbated by NLRP3 inflammasome-mediated release of IL-1β and IL-18." (PMID 38532054, 2024).
enteritis (5 papers, 2020 to 2025). Inflammation of the small intestine. "Our findings demonstrate that D-CONGA-Q7 significantly reduces the levels of pro-inflammatory cytokines TNF-α, IL-6, and IL-18, effectively alleviating small intestinal inflammation in a mouse model of enteritis induced by K88 (ETEC) exposure." (PMID 40136483, 2025). "Alternatively, intestinal epithelial cell-mediated SCFAs binds to the G protein-coupled receptor (GPR43) and activates the inflammasome-activating protein NLRP3, inducing the release of IL-18, which has a protective effect on enteritis." (PMID 38596637, 2024). "Collectively, IL-18 plays a dual role in the development of enteritis, promoting the progression of enteritis as an inflammatory factor, yet inducing tissue repair to prevent enteritis." (PMID 35707833, 2022). "Consistently, the serum concentrations of pro-inflammatory cytokines (IL-18 and IL-1β) were significantly increased in LPS-induced mice group, indicating the successful establishment of the enteritis model." (PMID 32950974, 2020). "In the piglet enteritis model, the intestinal epithelium NLRP3 inflammasome is abnormally activated, which can lead to a large release of pro-inflammatory cytokines such as interleukin-1β (IL-1β) and interleukin-18 (IL-18)." (PMID 39334766, 2024). "However, recently, several researches reveal that mice with IL-18 or IL-18 R knockout are more sensitive, rather than resistant, to dextran sulfate sodium (DSS)-induced enteritis and inflammatory bowel cancer." (PMID 35707833, 2022).
enterocolitis (5 papers, 2019 to 2024). An inflammatory process affecting the small intestine and colon. "Recently, a child carrying a gain-of-function NLCR4 mutation, developed severe enterocolitis and extremely elevated IL18 levels." (PMID 31253830, 2019). "Patients carrying the NLRC4 mutation with life-threatening enterocolitis could also benefit from such an antibody specific to IL-18 inhibition." (PMID 38983847, 2024). "In particular, patients carrying the NLRC4 mutation with life-threatening enterocolitis could potentially benefit from such an antibody specific to IL-18 inhibition." (PMID 33823154, 2021). "However, supplementing anakinra treatment with recombinant human IL-18BP, which is a circulating decoy protein for IL-18, was able to resolve MAS parameters as well as enterocolitis in this one NLRC4V341A-expressing AIFEC patient." (PMID 38090573, 2023).
Fever (5 papers, 2006 to 2023). Body temperature elevated above the normal range. "In conclusion, these data suggest that the evaluation of IL-1A, IL-1B and IL-18 gene SNPs can add useful information on the clinical course of patients affected by Mediterranean Spotted Fever, even if further confirmatory studies will be necessary." (PMID 36551320, 2022). "IL-18 and IL-1β are pro-inflammatory cytokines primarily produced by activated macrophages and both overlap in many functions but differ in signaling pathways with IL-1β being highly involved in pyrexia." (PMID 33228660, 2020). "Hay fever cases exhibiting IL4R Q576R GG, IL10(-819) TT or IL18(-137) CC genotype had also increased total IgE levels, although not significant due to low statistically power." (PMID 16759385, 2006).
Hashimoto thyroiditis (5 papers, 2018 to 2025). An autoimmune disorder caused by the production of autoantibodies against thyroid tissue. "In Hashimoto thyroiditis, the serum levels of IL-2, IL-18, and IFNγ are higher in these patients." (PMID 40429402, 2025). "In addition, previous studies on the thyroid tissues of patients with Hashimoto’s thyroiditis revealed upregulated IL-18 expression in TFCs located near infiltrating lymphocytes; this is similar to the distribution of inflammasome-related pattern recognition receptors in our study." (PMID 29915579, 2018). "Activation of the inflammasome by IL-β and IL-18 produced by macrophages is one of the mechanisms of pyroptosis in the course of Hashimoto’s thyroiditis, involving Gram-negative bacteria and NLRC4." (PMID 38999993, 2024).
hepatitis B (5 papers, 2008 to 2023). "Similarly in other studies, higher concentrations of plasma circulating cytokines IL-18 and IL-1β were observed in hepatitis B patients." (PMID 34161370, 2021). "In conclusion, this study suggested that for hepatitis B virus infection, IL-12 and IL-18 rather than IL-21 were more suitable for assessing disease severity of high viral load (5-6log10) patients and IL-21 was more suitable for patients with low viral load (3-4log10)." (PMID 36383803, 2022).
hepatitis C (5 papers, 2016 to 2021). "Therefore, we next studied the potential association between the IL-28B genotype and monocyte production of IL-12 and IL-18, respectively, in hepatitis C." (PMID 27583440, 2016). "In the present study, we analyzed whether polymorphisms in inflammasomes genes IL1B rs16944, IL18 rs187238, NLRP3 rs10754558, CARD8 rs2009373, CTSB rs1692816 and AIM2 rs1103577 are associated with susceptibility to HCV infection and liver fibrosis in hepatitis C patients in the Amazon population." (PMID 34161370, 2021). "Similarly, heterozygote carriers for CTSB rs1692816 and AIM2 rs1103577 (padj = 0.008) or for IL18 rs187238 and NLRP3 rs10754558 (padj = 0.005), have less chances to the development of hepatitis C." (PMID 34161370, 2021).
ileitis (5 papers, 2019 to 2025). "It was previously shown that IL-22 can upregulate IL-18 production from intestinal epithelial tissues to enhance immune cell IFNγ production in T. gondii-induced ileitis." (PMID 36361787, 2022). "Thus, sustained IL-22 and IL-18 production promoted intestinal inflammation in the high dose oral infection model, as IL-22-/- and IL-18-/- mice exhibited significantly less infection-induced ileitis." (PMID 34938670, 2021). "This ileitis is due to the strong T-helper 1 biased immune response, characterized by the overproduction of pro-inflammatory mediators including; IFN-γ, TNFα, IL1β, IL18, and NO, commonly known as “cytokine storm”." (PMID 38743178, 2024).
infarction (5 papers, 2019 to 2025). A localised pathological necrosis of tissue resulting from obstruction of the blood supply usually by a thrombus, an embolus, or vascular torsion. "Furthermore, the inflammasome-associated inflammatory cytokine IL-18 was significantly upregulated in the infarction area and border zone, which was also suppressed by RSV treatment." (PMID 32908628, 2020). "Moreover, injection of AAV-miR-30e-3p in CME- induced MI in a rat model limited infarct size, improved cardiac function, and reduced the serum level of cTnI, IL-18, and IL-1β." (PMID 38132140, 2023).
interstitial lung disease (5 papers, 2019 to 2024). A diverse group of lung diseases that affect the lung parenchyma. "In another study to ascertain the involvement of IL-18 in PM and DM inflammation, 33 patients with DM and 16 patients with PM were enrolled in the study (there were some patients with interstitial lung disease in both groups)." (PMID 36032110, 2022). "These authors along with others concluded that serum IL-18 levels were strikingly elevated in DM and PM patients and particularly in DM patients complicated with interstitial lung disease." (PMID 36032110, 2022). "Serum IL-18, IL-6, IL-10, and IFN-β were increased in DM patients with interstitial lung disease as well." (PMID 32644977, 2020). "Furthermore, thalidomide reduces lipopolysaccharide‐stimulated release of TNF‐α, IL‐8, and IL‐18 (‘necrotic’ cytokines), but not IL‐6, IL‐10, and IL‐12 (p70) (‘inflammatory’ cytokines) from alveolar macrophages in patients with interstitial lung disease." (PMID 38481033, 2024). "Moreover, patients with DM had higher levels than PM patients, and DM patients with interstitial lung disease (ILD) had higher IL-18 serum levels than DM patients without ILD." (PMID 32775472, 2020).
intestinal inflammation (5 papers, 2019 to 2025). "In DSS-induced experimental colitis the administration of IL-18BP or the neutralization of IL-18 was able to attenuate intestinal inflammation and weight loss." (PMID 37645250, 2023). "Moreover, the upregulation of IL-18 is central to the pathogenesis of tissue destruction and the severity of gastroenteritis in humans and mice." (PMID 37288274, 2023).
leukocytosis (5 papers, 2021 to 2026). "When exploring this, cell numbers (platelets, white blood cells), neutrophil counts, S100 proteins, CRP, ESR, ferritin, leukocytosis with neutrophilia, serum amyloid, and IL-18 should be considered." (PMID 37771977, 2023).
male infertility (5 papers, 2018 to 2025). The inability of the male to effect fertilization of an ovum after a specified period of unprotected intercourse. "Interleukin-17 and Interleukin-18 belong to those cytokines recently receiving a fair amount of attention in the etiopathogenesis of male infertility." (PMID 40806758, 2025). "Increased concentrations of IL-18 and MIF have previously been implicated in male infertility and reduced sperm motility." (PMID 36304709, 2020). "No significant causal relationship was found between IL-18 and male infertility." (PMID 40226698, 2024). "IL-18 is a less known molecule, which may increase particularly during autoimmune pathologies and contribute to the formation of antisperm antibodies that are a common reason for male infertility during systemic inflammation." (PMID 36405233, 2022). "This study aimed to investigate the possible influence of interleukins IL-17 and IL-18, and prostaglandins PGE2 and PGF2α on male infertility." (PMID 40806758, 2025). "Gossypol-induced male infertility markedly and significantly increased the levels of testicular TBARS, NO, TNF-α, ADAM-17, and interleukins (IL-1β, IL-6, and IL-18) while significantly decreasing the levels of both TIMP-3 and IL-12 compared with those of the control group." (PMID 29849861, 2018).
non-Hodgkin lymphoma (5 papers, 2021 to 2024). Distinct from Hodgkin lymphoma both morphologically and biologically, non-Hodgkin lymphoma (NHL) is characterized by the absence of Reed-Sternberg cells, can occur at any age, and usually presents as a localized or generalized lymphadenopathy associated with fever and weight loss. "In a first-in-human study, IL-18 secreting autologous anti-CD19 CAR-T cells (huCART19-IL18) exhibit controllable toxic characteristics and satisfactory efficacy in patients with non-Hodgkin lymphomas relapsed or refractory to prior CAR-T cell therapy." (PMID 38664743, 2024). "Recently, a phase I clinical trial was initiated to evaluate the best dose, possible benefits, and side effects of interleukin-18-secreting autologous anti-CD19 CAR T-Cells (huCART19-IL18) in treating patients with non-Hodgkin's lymphoma (NHL), CLL, and ALL." (PMID 37577033, 2023).
peripheral nerve injury (5 papers, 2015 to 2021). Injury to a peripheral nerve. "Several studies demonstrated that the development of neuropathic pain after peripheral nerve injury is associated with spinal upregulation of mRNA and the protein level of IL-18 and its specific receptor, IL-18R." (PMID 28337574, 2017). "Previous reports suggest that increased production of pronociceptive interleukins (e.g., IL-1β, IL-18, and IL-6) by immune and glial cells after peripheral nerve injury contributes to the development and maintenance of neuropathic pain." (PMID 34681732, 2021). "A recent report suggests that interleukin-18 (IL-18), a pro-inflammatory cytokine, acts as a messenger between microglia and astroglia after peripheral nerve injury." (PMID 28954391, 2017). "In agreement to our hypothesis, Tzekova and colleagues have demonstrated in Schwann cell cultures that IVIg induce axonal outgrowth by secreting interleukin-18 (IL-18), a proinflammatory cytokine transiently induced after peripheral nerve injury." (PMID 30131066, 2018). "IL-18 was also found to be transiently induced after peripheral nerve injury." (PMID 26022648, 2015).
Pleural effusion (5 papers, 2014 to 2025). The presence of an excessive amount of fluid in the pleural cavity. "In the BALF of children with SCAP complicated with pleural effusion (PE), the levels of IL-18, the IL-18/IL-38 ratio, and the IL-33 level were significantly elevated (P < 0.05)." (PMID 40352606, 2025). "In the two pleural effusion samples, the cytokines with the highest concentrations were IL-1ra (40,735.95 pg/ml for Gp4-8-2021, 9016.76 pg/ml for Gp4-9-2021) and IL-18 (3237.45 pg/ml for Gp4-8-2021 and 2764.82 pg/ml for Gp4-9-2021)." (PMID 35668452, 2022). "The concentration of IL-2, IL-12, IL-18 and IL-23 in supernatants from Mtb-stimulated blood PBMCs and cells from pleural effusions of TB patients were measured by Luminex method." (PMID 27586092, 2016). "The IL-2, IL-12, and IL-18 production was higher in supernatants of cells from pleural effusions than blood PBMCs, while IL-23 production was lower in supernatants of cells from pleural effusions; however, only the difference in IL-2 production was statistically significant." (PMID 27586092, 2016). "Although some studies reported predictive factors for a poor response to treatment in cases of MP pneumonia such as LDH, interleukin 18, and ferritin levels, to date, no study has focused on the clinical significance of pleural effusion in MP pneumonia." (PMID 34578108, 2021).
renal dysfunction (5 papers, 2009 to 2023). "With the use of the RFC model, serum KIM-1, IL-18, and NGAL may serve as markers of incipient renal dysfunction in children after HSCT." (PMID 37958774, 2023). "The aim of this study was to assess the serum concentrations of damage markers (KIM-1, IL-18, NGAL) in children undergoing HSCT and confront them with the classical functional markers (creatinine, cystatin C), and hyperfiltration being the surrogate marker of renal dysfunction." (PMID 37958774, 2023).